CALR (calreticulin)
Diseases named in the same sentence as CALR in open-access papers (continued):
Sharing a sentence is not in itself a finding about the gene and the disease.
pancreatic cancer (continued). "Similar to the characterisation of EVs from human pancreatic cancer cell lines, Alix, TSG101 and CD9 were detected whereas calreticulin and GAPDH were undetected in the P100 fractions from KPC and TPAC cells after ultracentrifugation." (PMID 39863771, 2025). "When pancreatic cancer was treated with EBR, ER stress is augmented in a dose-dependent manner and CALR and CALNX expressions were increased as suggested by our group in recent studies." (PMID 37529796, 2022). "ICD is characterized by calreticulin expression and high‐mobility group box 1 (HMGB1) release in dying Kras‐induced pancreatic cancer (KPC) cells, which is demonstrated in a vaccination experiment to prevent KPC tumor growth on the contralateral site." (PMID 33747719, 2021). "In the current study, TTFields application significantly suppressed c-Myc expression and induced immunogenic cell death (ICD)-characterized by increased calreticulin cell-surface exposure, extracellular ATP secretion, and elevated HMGB1 release-in pancreatic cancer models." (PMID 41760592, 2026). "This similar even much stronger phenomenon observed in prostate adenocarcinoma suggested the potential universality of CALR‐immune checkpoint interplay, at least not merely in pancreatic cancer." (PMID 32508042, 2020). "Furthermore, CALR was significantly correlated with key immunity‐killing molecules, including PRF1, GZMB, and IFNG in pancreatic cancer." (PMID 32508042, 2020). "Moreover, CALR promotes epidermal growth factor (EGF)-triggered EMT via the Integrin/EGFR/ERK/MAPK pathway and alters intracellular Ca2+ levels in the pancreatic cancer cells." (PMID 33221760, 2020). "Thus, upregulating CALR rather than targeting immune checkpoints represents a potentially more efficient approach for pancreatic cancer therapy." (PMID 32508042, 2020). "In addition, high CALR expression largely favored the OS and DFS of pancreatic cancer patients." (PMID 32508042, 2020). "In the same study, calreticulin was found to be co-localized with pEGFR1173, fibronectin, and integrin β1, while being co-immunoprecipitated with fibronectin, integrin β1, and c-Myc, which suggests the direct involvement of calreticulin in the regulation of EGF-induced EMT in pancreatic tumors." (PMID 32268506, 2020).
viral infection (19 papers, 2014 to 2025). "However, recent research showed that cells undergoing programmed death following bacterial or viral infection release signals, including surface-exposed calreticulin (CRT), damage-associated molecular patterns (DAMPs), and high-mobility-group protein 1 (HMGB1)." (PMID 38067345, 2023). "We now show that viral infection with XVir significantly increased both calreticulin (CALR) surface expression (‘eat-me’) and CD47 surface expression (‘don’t-eat-me’) on all assessed tumors cells." (PMID 38357194, 2024). "The C-type lectin MjsvCL presents virions to the cell-surface receptor calreticulin to promote viral infection by interacting with the viral protein VP28." (PMID 37158899, 2023). "The CALR protein showed increased levels of arginylation in both transfections, as well as in the whole virus infection model." (PMID 36851505, 2023). "CALR decrease has been described in other viral infections (influenza virus, SFV, or VSV) leading to accelerated maturation of cellular and viral glycoproteins, with a modest decrease in the folding efficiency." (PMID 36851505, 2023). "Compared to the mock infection, all the cancer cell lines were found to increase surface expression of calreticulin and release ATP after virus infection." (PMID 31209267, 2020). "Other upregulated ER-stress proteins including calreticulin and calnexin important for calcium storage and protein folding were shown to act crucial role in viral infections." (PMID 31751365, 2019). "At early stages of virus infection, calreticulin showed a typical lamellae structure formed around the cell nucleus." (PMID 24517969, 2014). "Furthermore, the IRE1α-XBP1 axis promotes fibronectin-rich matrix deposition during viral infection, and calreticulin-mediated ER stress facilitates TGF-β signaling and ECM assembly in fibrotic tissues." (PMID 40501821, 2025). "Calreticulin increase was also significant in H29 post virus infection." (PMID 38494863, 2024). "In addition, the viral infection of these cancer cells promoted the translocation of calreticulin (CRT) to the cell surface." (PMID 38921005, 2024). "Interestingly, KDEL receptors as well as the chaperones GRP78, calreticulin, and calnexin are up-regulated by cells under stress conditions and viral infections as part of the stress response." (PMID 30621148, 2019). "In addition, viral infection and hyperthermia each cause an endoplasmic reticulum stress response, change the expression of HSP 70/90 and the surface properties (calreticulin) of tumor cells, and induce immunogenic tumor cell death mechanisms." (PMID 25364402, 2014). "ER chaperones are important molecules involved in the ERS, among which two critical chaperone systems, calnexin/calreticulin, and GRP78/GRP94, have been widely studied for their roles in viral infection." (PMID 35562870, 2022). "A total of sixty-five proteins bind to chLGP2, seventeen of which are shared in both cells, like calreticulin, TRBP, endoplasmic reticulum chaperone protein Bip, and studies have shown they exert in virus infection to a certain extent." (PMID 35145497, 2021). "In particular, calreticulin, the ubiquitin machinery, and the 26S proteasome are most commonly identified components of the UPR and ERAD machinery that also regulate virus infection." (PMID 24653727, 2014). "Furthermore, the expression of the ‘eat-me’-signal calreticulin (CALR) on the tumor surface and the ‘don’t-eat-me’-signal CD47 was assessed during viral infection." (PMID 38357194, 2024). "For example, CALR suppresses IFN-α production and antiviral activity in the context of hepatitis B virus infection, ERAP1 induces cleavage of cytokine receptors, and syndecan-4 (SDC4) negatively regulates retinoic acid-inducible gene I (RIG-I)-mediated signalling during virus infection." (PMID 35727847, 2022).
viral infection (continued). "The results showed that EDEM1 gene, calreticulin, and calnexin mRNA levels were all not modified in cp BVDV-infected MDBK cells, indicating that viral infection did not activate the ATF6 and XBP1 signaling pathways." (PMID 36939351, 2023).
bladder cancer (17 papers, 2009 to 2025). "Two deaths occurred in the CALR-mutated subgroup after 6.1 and 8.0 years of therapy, respectively (one due to leukemic transformation, one due to urinary bladder cancer)." (PMID 41463191, 2025). "Overexpression of calreticulin has been observed in some bladder cancer studies and correlates with features like advanced stage and potentially poorer prognosis." (PMID 41427025, 2025). "Further research is needed to fully elucidate CALR′s specific contributions to bladder cancer and its potential as a biomarker or therapeutic target." (PMID 41427025, 2025). "Calreticulin has been shown to increase adhesion of bladder cancer cells by stabilizing mRNA for fucosyltransferase 1 (FUT-1), an enzyme responsible for α-1,2-linked fucosylation of β1 integrin." (PMID 36430846, 2022). "Elevated CALR expression was showed by 2-DE, western blot analysis, and immunohistochemistry in the urine and tissues of patients with bladder cancer." (PMID 24884814, 2014). "It has been reported that the expressions of CALR in both tumor tissue and urine of patients with bladder cancer were higher than in those of healthy people." (PMID 24884814, 2014). "Increased levels of calreticulin have been reported in hepatocellular, colon, prostate and bladder carcinomas and as well as in radioresistant squamous carcinoma." (PMID 19367286, 2009). "Additionally, knockdown of calreticulin suppresses the growth, adhesion, and migratory ability of the cells and blocks in vivo metastasis in bladder cancer." (PMID 30974841, 2019). "Furthermore, increased expression of CALR was a poor prognostic factor in diverse tumours including neuroblastoma, bladder cancer, and non-Hodgkin’s lymphoma." (PMID 27566066, 2016). "Similarly, the presence of the 1O2 quencher l-histidine decreased calreticulin translocation in hypericin treated bladder cancer cells." (PMID 25688334, 2015). "In addition to the role of HMGB1 in ICD, it was found that upon hypericin treatment of bladder cancer cells or upon oxaliplatin or doxyrubicin treatment high levels of ATP were secreted, which like calreticulin also preceded apoptotic PS exposure." (PMID 25688334, 2015). "Research suggests that CALR expression may be dysregulated in bladder cancer tissues." (PMID 41427025, 2025). "In addition, serum IgG levels of anti-calreticulin autoantibodies have been found to be significantly higher in bladder cancer patients than in normal controls, leading to the proposal of anti-calreticulin antibodies as a novel biomarker for bladder cancer progression." (PMID 25386408, 2014). "Furthermore, HC-5404 and anti-PD-1 combination therapy significantly enhanced antitumor efficacy in a syngeneic mouse bladder cancer model, correlated with increased immune activation markers on tumor cells and TAMs, including IFNAR1 and calreticulin, and reduced immunosuppressive activity of MDSCs." (PMID 41372991, 2025).
neuroblastoma (16 papers, 2009 to 2025). Neuroblastoma (NB) is the most common solid, extracranial childhood tumor. "The off-target lorlatinib-resistant neuroblastoma cell line (CLB-Ga-LR1000) also experienced the upregulation of CALR after incubation with lorlatinib (1.0 μM) for 20 h." (PMID 39767726, 2024). "Overall, the findings of this study demonstrate that treatment with angiotensin-converting enzyme inhibitors promotes the expression of calreticulin, low-density lipoprotein-receptor-related protein 1B, and 14-3-3 protein zeta/delta in neuroblastoma cells." (PMID 37630190, 2023). "While in bladder cancer (n=30), mantle cell lymphoma (n=92), and neuroblastoma (n=251), calreticulin levels correlate with poor overall survival." (PMID 33821233, 2021). "On one hand, calreticulin expression—in the context of chemotherapeutic treatment—in acute myeloid leukemia (n=20), colorectal cancer (n=68), neuroblastoma (n=68), and ovarian cancer (n=22) is favorable." (PMID 33821233, 2021). "In contrast, thapsigargin induced both ER stress and calreticulin release in neuroblastoma and MEFs." (PMID 25688334, 2015). "Previous research has shown that GABARAP interacts directly with CALR in vitro and it co-localizes (punctuate structure) and co-immunoprecipitates with CALR in the mouse neural precursor and neuroblastoma model N2a (Neuro 2A) cells, as well as in AMO1 multiple myeloma cells, respectively." (PMID 40650127, 2025). "Indeed, levels of cell membrane expressed calreticulin were enhanced in thapsigargin treated neuroblastoma cells, which were genetically manipulated to have reduced Ca2+ levels in the ER." (PMID 25688334, 2015). "Calreticulin has also been identified as a prognostic factor for neuroblastoma." (PMID 24134804, 2013). "In the myenteric plexus, the proportions of neurons expressing either or both calbindin (CalB) and calretinin (CalR), two calcium-binding proteins that are expressed by the major subpopulations of excitatory neurons, were unchanged following Nb infection and not impacted by eosinophil deficiency." (PMID 39141685, 2024). "As with Calreticulin, GRP75/Mortalin has previously been identified as a possible biomarker for cancer and cardiovascular diseases as well as being a potential prognostic factor for neuroblastoma." (PMID 24134804, 2013).
gastric cancer (15 papers, 2013 to 2024). A primary or metastatic malignant neoplasm involving the stomach. "In gastric cancer patients, positive immunohistochemical staining of CALR is associated with poor overall survival; moreover CALR is an independent prognostic indicator for the survival of gastric cancer patients." (PMID 33221760, 2020). "For example, CALR overexpression enhances angiogenesis, and facilitates proliferation and migration of gastric cancer cells, which is in line with the association of CALR with tumor invasion, lymph node metastasis, and poor survival in gastric cancer patients." (PMID 29228584, 2017). "In addition, higher expression of CALR is also associated with the more aggressive malignant processes and poorer prognosis in esophageal cancer, gastric cancer and breast ductal carcinoma, which is also confirmed in our study." (PMID 34910788, 2021). "In gastric cancer, some researchers found that CALR overexpression was associated with GC invasion, metastasis, lymph node metastasis, angiogenesis, and GC patients’ survival." (PMID 35641480, 2022). "And the elevated expression of CALR has been demonstrated to enhance the migratory capacity of gastric cancer cells in both in vivo and in vitro studies." (PMID 39479348, 2024). "Evidence suggests that CALR expression is elevated in gastric cancer compared to normal tissue levels, and this increase is associated with lymph node metastasis as well as overall metastatic potential." (PMID 39479348, 2024). "Higher expression levels of ADAR1, CALR and β-catenin proteins were found in peritoneal metastasis than gastric cancer tissues." (PMID 35003354, 2021). "We further performed immunohistochemistry to detect ADAR1 and CALR expression in gastric cancer peritoneal metastatic tissues of nude mice." (PMID 35003354, 2021). "Mechanically, ADAR1 knockdown distinctly reduced oncogene CALR expression as well as inactivated Wnt / β-catenin pathway in gastric cancer cells." (PMID 35003354, 2021). "Here, this study detected ADAR1, CALR and β-catenin in primary gastric cancer and peritoneal metastasis tissues." (PMID 35003354, 2021). "We found that ADAR1 was mainly expressed in the nucleus in gastric cancer tissues, while CALR was primarily distributed in the cell cytoplasm and membrane in gastric cancer tissues." (PMID 35003354, 2021). "Immunofluorescence results confirmed the co-localization of ADAR1 with CALR, E-cadherin, Vimentin, and β-catenin proteins in normal and gastric cancer tissue samples." (PMID 35003354, 2021). "In cancer, CALR is proposed as a prognostic marker in gastric cancer and esophageal squamous cell carcinoma." (PMID 33499132, 2021). "Expression of ADAR1, CALR and β-catenin proteins was detected in 4 pairs of normal and gastric cancer tissues via western blot." (PMID 35003354, 2021). "Consistently with previous research, CALR was overexpressed in gastric cancer, and its up-regulation was distinctly correlated to lymph node metastasis and peritoneal metastasis." (PMID 35003354, 2021). "From TCGA database, CALR displayed a significantly positive correlation with ADAR1 across gastric cancer samples." (PMID 35003354, 2021). "After quantification, ADAR1 and CALR were both highly expressed in gastric cancer than normal tissues." (PMID 35003354, 2021). "As a result, ADAR1, CALR and β-catenin were all significantly overexpressed in gastric cancer than normal tissues." (PMID 35003354, 2021). "In conclusion, the present study suggests that miR-637 participates in ER stress-induced apoptosis in gastric cancer cells by suppressing CALR expression." (PMID 33209200, 2020). "In conclusion, the present study suggests that miR-637 participates in the ER stress-induced apoptosis in gastric cancer cells by suppressing CALR expression." (PMID 33209200, 2020). "CALR was highly expressed in gastric cancer, breast cancer, and other tumors, which was related to migration, invasion and abnormal apoptosis of tumor cells." (PMID 31632490, 2019).
gastric cancer (continued). "Calreticulin positively regulates vascularization through the activation of vascular endothelial growth factor (VEGF) in gastric cancer." (PMID 30974841, 2019). "CALR up-regulation significantly reinforced angiogenesis and metastasis in gastric cancer." (PMID 35003354, 2021). "We further observed the roles of ADAR1 on CALR and β-catenin in gastric cancer by western blot." (PMID 35003354, 2021). "Thus, targeting ADAR1 suppressed CALR and β-catenin expression in gastric cancer." (PMID 35003354, 2021). "Also, its expression was distinctly higher in metastatic lymph nodes than primary tumors, indicating that CALR could be involved in malignant transformation of gastric cancer." (PMID 35003354, 2021). "miR-637 or CALR may be a future potential target for gastric cancer treatment." (PMID 33209200, 2020). "We performed western blot to observe the effects of ADAR1 knockdown on CALR expression, Wnt / β-catenin pathway and EMT process in gastric cancer cells." (PMID 35003354, 2021). "Collectively, ADAR1 knockdown suppressed CALR expression, Wnt / β-catenin pathway as well as EMT process in gastric cancer cells." (PMID 35003354, 2021). "CALR silencing inhibits TGF-β1-induced suppression of E-cadherin, thereby decreasing the invasiveness and migration of gastric cancer cells." (PMID 33221760, 2020). "In gastric cancer, CALR can promote tumor angiogenesis, local invasion and lymph node metastasis, which is a good biomarker of prognosis in gastric cancer." (PMID 31632490, 2019).